SIRT1 (sirtuin 1)
Diseases named in the same sentence as SIRT1 in open-access papers (continued):
Sharing a sentence is not in itself a finding about the gene and the disease.
uterine cancer (1 paper, 2020). Primary or metastatic malignant neoplasm involving the uterine corpus and/or the cervix. "SIRT1 expression seems to be associated with improved progression-free survival in uterine cancer (endometrioid and clear-cell) and is correlated to the tumor suppressors β-Catenin and ARID1A." (PMID 32388637, 2020). "Many studies exist observing the prognostic value of different epigenetic changes in uterine cancers, but less is known about the role of SIRT1 in these cancer types." (PMID 32388637, 2020). "Our results show that an increased SIRT1 expression in uterine cancer types (endometrioid and clear-cell) is correlated to a longer progression-free survival which supports the thesis that SIRT1 acts as a tumor suppressor." (PMID 32388637, 2020). "Both correlations support our thesis that SIRT1 functions as tumor suppressor in the examined uterine cancer types." (PMID 32388637, 2020).
uterine tumors (1 paper, 2020). "Furthermore, progression-free survival was better in patients with SIRT1 overexpressing uterine tumors, while only a trend was observed in regard to overall survival." (PMID 32388637, 2020).
vitamin B12 deficiency (1 paper, 2023). A disease characterized by low serum levels of vitamin B12, either inherited or acquired. "Interestingly, Ppargc1a is activated by Sirt1 diacylation, whose expression, in turn, is downregulated in vitamin B12 deficiency owing to reduced activity of methionine synthase." (PMID 37369025, 2023).
Werner syndrome (1 paper, 2019). "Interestingly, SIRT1-mediated homologous recombination may require WRN, a helicase and exonuclease mutated in the premature ageing Werner syndrome." (PMID 30666570, 2019).
Wilson disease (1 paper, 2023). A very rare inherited multisystemic disease presenting non-specific neurological, hepatic, psychiatric or osseo-muscular manifestations due to excessive copper deposition in the body. "In this work, we aimed to reveal the mechanisms of GDL alleviate nerve injury through PI3K/Akt/FoxO1 and Sirt1/FoxO1 signaling pathways to inhibit autophagy in the rat models of Wilson's disease." (PMID 38010098, 2023).
xeroderma pigmentosum (1 paper, 2011). Xeroderma pigmentosum (XP) is a rare genodermatosis characterized by extreme sensitivity to ultraviolet (UV)-induced changes in the skin and eyes, and multiple skin cancers. "Thus, downregulation of SIRT1 significantly sensitized cells to UV irradiation through interaction with xeroderma pigmentosum group A (XPA), a core factor essential for NER." (PMID 22247744, 2011). "SIRT1 also regulates other DNA repair pathways, viz. base-excision repair (BER) and nucleotide-excision repair (NER) through the transcription of xeroderma pigmentosum (XPA, XPC) group proteins." (PMID 22247744, 2011).
cancer (1,040 papers, 2006 to 2026). A tumor composed of atypical neoplastic, often pleomorphic cells that invade other tissues. "In this context, the histone deacetylases sirtuins (SIRT1-7) regulate key biological processes like genomic stability, inflammation, cellular senescence, and metabolic functions, increasingly linked to cancer." (PMID 41898317, 2026). "SIRT1, a deacetylase nuclear protein, has been previously implicated in various diseases, especially those related to aging and cancer." (PMID 40486531, 2025). "Sirt1 expression is implicated in mitigating excess ROS in cancer cells, leading to increased cancer cell signaling, proliferation and resistance to chemotherapy treatments." (PMID 41436543, 2025). "The relationship between SIRT1 expression and cancer progression, as well as its underlying mechanisms, remains elusive." (PMID 41020376, 2025). "As a result, SIRT1 is implicated in aging and is associated with a range of conditions, such as cancer, cardiovascular diseases, and neurodegenerative disorders." (PMID 39636756, 2025). "SIRT1 activation by resveratrol mimics some effects of CR, enhancing autophagy and improving metabolic health, thereby reducing cancer risk." (PMID 39940361, 2025). "In one study, overexpression of SIRT1 in the tumor microenvironment, mediated by cancer-associated adipocyte-derived extracellular vesicles, upregulated CD24 expression, promoting tumorigenesis and immune evasion in mice." (PMID 41471349, 2025). "Although the SIRT1-NF-κB pathway has significant anti-senescence effects, its mechanisms associated with cancer cell senescence and immune cell senescence remain to be further explored." (PMID 40292294, 2025). "The delivery of SIRT1 by cancer-associated adipocyte-derived extracellular vesicles (CAA-EVs) significantly alters immune cell populations within the tumor microenvironment, contributing to ovarian cancer cell survival." (PMID 40330466, 2025). "By promoting the Warburg effect, SIRT1 causes cancer cells to prefer glycolysis over oxidative phosphorylation for energy, even when oxygen is present—which also contributes significantly to tumor growth and invasiveness through lactate production." (PMID 40427612, 2025). "Dysregulation of SIRT1 is related to various age-associated disorders such as cardiovascular and neurodegenerative diseases, and cancer." (PMID 41304943, 2025). "Although SIRT1 was downregulated in various cancers, SIRT1 expression was associated with different immune cells, such as Th2 cells and memory T cells, indicating that modulation of SIRT1 activity would reprogram the immune landscape in the tumor." (PMID 41425553, 2025). "The association between increased SIRT1 expression and improved prognosis in various cancers further supports the role of Gln-K604 as a central metabolic signal for proliferation." (PMID 40338031, 2025). "This study focused on ROS-mediated cancer cell death because ROS are associated with a variety of cellular processes involving both Sirt1 and Sirt6." (PMID 38254877, 2024). "One study reveals that glycolytic cancer-associated fibroblasts (CAFs) secrete lactate, inducing SIRT1-dependent deacetylation and the degradation of T-bet in CD4+ T cells, thereby suppressing the Th1 immune response." (PMID 39796040, 2024). "We analyzed mutations in the SIRT1 gene across cancers via the cBioPortal online database and found that SIRT1 mutations were most frequent in UCEC, BLCA, UCS, STAD, and CHOL." (PMID 39845948, 2024).
cancer (continued). "Targeting SIRT1 and its associated pathways presents a promising strategy to manipulate autophagy in cancer treatment." (PMID 39403142, 2024). "Mutations and widespread polymorphisms of SIRT1 were discovered in cancer lines produced by Chinese and Japanese individuals as well as 41 cancer lines." (PMID 39403142, 2024). "In terms of diagnostic value, our study demonstrated that SIRT1 has high diagnostic sensitivity in various cancers, particularly in KICH and ESCC, where the AUC values were 0.923 and 0.902, respectively, indicating extremely high diagnostic efficacy." (PMID 39845948, 2024). "Second, this study presents only preliminary evidence of the associations between SIRT1 and various cancers." (PMID 39845948, 2024). "Reduced concentrations of SIRT1–3 have been observed in older adults with frailty syndrome, a condition often associated with cancer." (PMID 39727710, 2024). "SIRT1 also regulates the symbiosis between cancer-associated fibroblasts (CAFs) and cancer cells, significantly influencing oncogenic signaling cascades." (PMID 39796040, 2024). "In most cancer types, increased SIRT1 expression is positively associated with eosinophils, helper T cells, central memory T cells, effector memory T cells, γδ T cells, and Th2 cells." (PMID 39845948, 2024). "It explores SIRT1’s association with cancer hallmarks and its interactions with apoptosis and ferroptosis." (PMID 39403142, 2024). "Silencing SIRT1 not only induced apoptosis in cancer cells but also caused a significant reduction in their migration and invasion abilities." (PMID 37242510, 2023). "Although the exact role of SIRT1 is not well understood, it has been implicated in tumor growth and resistance to therapy in several types of cancer, including CRC." (PMID 37107301, 2023). "Increased thyroid tissue SIRT1 expression has been found to be associated with cancer progression and worse prognosis for PTC patients." (PMID 37173902, 2023). "KRAS mutations increase levels of a protein called SIRT1, and this interaction boosts cancer cell proliferation and tumour growth." (PMID 37779142, 2023). "Although the role of SIRT1 is essential in maintaining ovarian function, its mutation often causes cancer in ovarian tissues." (PMID 36975503, 2023). "To that end, we measured the prevalence of R-loops in an isogenic system of cancer cells deficient or proficient in SIRT1, and in U2OS cells harboring an inactive SIRT1 mutant (H363Y, henceforth referred to as H3Y/Mut)." (PMID 37998365, 2023). "Upregulation of SIRT1 has been associated with various cancers, but the opposite, that is, a protective role of SIRT1 against some cancers, has also been reported." (PMID 35883477, 2022). "Studies have also reported that the expression levels of SIRT1 are linked with cancer invasion/metastasis and drug resistance, which in turn affect the prognosis of cancers." (PMID 35548580, 2022). "In CRC it has been demonstrated that lncH19 mediates 5-FU resistance enforcing SIRT1 mediated autophagy, while its expression by cancer-associated fibroblasts, promotes stemness and chemoresistance of CRC." (PMID 35596172, 2022). "High SIRT1 expression is found in several cancer cell lines and is associated with poor prognosis and survival." (PMID 35054489, 2022). "Simultaneously, SIRT1 acts as a protective gene in certain types of cancers, including gastric and breast cancer, and its deficiency accelerates cancer progression and chemoresistance." (PMID 35855334, 2022). "SIRT1 is associated with multiple diseases, including cancer, vascular diseases and neurodegenerative disorders." (PMID 37868628, 2022).
cancer (continued). "SIRT1 overexpression has been shown to cause tumor growth and a significant increase in the cell survival ability of cancer cells." (PMID 36142156, 2022). "The overexpression of SIRT1 in cancer is associated with the need for chemotherapy, development of resistance to ionizing radiation, and silencing of tumor suppressor genes." (PMID 35163511, 2022). "Sirtuin 1 (SIRT1) is a protein deacetylase that regulates the activity of several proteins implicated in cancer development and progression." (PMID 35212616, 2022). "SIRT1 is proved to be highly involved in cancer because of its underlying functions in tumorigenesis 99-101, senescence 102, 103, immunity 104, 105 and inflammation." (PMID 33390835, 2021). "In breast cancer, loss of SIRT1 enhances the secretion of pro-tumorigenic exosomes and promotes cancer invasion." (PMID 33390835, 2021). "In models with hepatoma HepG2, the elevated radioresistance of hypoxic cancer cells is associated with the hypoxia-induced deacetylation/stabilization of c-Myc by Sirt1." (PMID 33806538, 2021). "The expression of SIRT1 is closely associated with the proliferation, survival, and resistance of many types of malignant tumors." (PMID 34381712, 2021). "Based on human cancer-associated data, previously reported in the literature, SIRT1 serves as a tumor promoter." (PMID 33917352, 2021). "In gastric cancers, SIRT1 was associated with lymphatic invasion, vessel invasion, lymph node metastasis and a poor cancer-specific survival." (PMID 34638362, 2021). "Nonetheless, CHC, a classical MCT inhibitor with more affinity for MCT1, led to enhanced SIRT1 expression, decreased histone acetylation, and N-cadherin expression, associating with reduced cell migration in cancer and normal kidney cell lines." (PMID 32340156, 2020). "Taken together, these survival analyses support the idea that higher SIRT1 expression correlates to prolonged OS in patients with cancers, particularly those carrying RAS mutations." (PMID 32276460, 2020). "Under massive levels of DNA damage and loss of tumor suppressors or checkpoints, SIRT1 overexpression promotes cancer formation." (PMID 32878301, 2020). "According to the TCGA and Gene Expression Omnibus (GEO) databases, we also found that SIRT1 overexpression was correlated to better prognosis in human patients with cancers that frequently carry oncogenic RAS mutations." (PMID 32276460, 2020). "Nevertheless, experiments have shown that mice with overexpression of SIRT1 have lower cancer risk and less metabolic dysfunction." (PMID 32388637, 2020). "Recently, a report shows that the mutation of SIRT1 led to a decreased risk of HCC 25 reminds us that the complete function of SIRT1 is necessary to promote cancer progression." (PMID 32714081, 2020). "In sum, although it is clear that SIRT1 is implicated in cancer, its precise role in tumorigenesis is still controversial." (PMID 32636443, 2020). "Taken together, our data suggest that inhibition of SIRT1 by MHY2245 causes inhibition of cancer cell metabolism by decreasing PKM2 expression." (PMID 32398958, 2020). "Meanwhile, overexpression of SIRT1 was also reported in several cancers and associated with an unfavorable prognosis." (PMID 32158696, 2020). "Pharmacological interventions for increasing SIRT1 activity have been reported to delay aging, and associated disorders such as obesity, inflammation, cancer, autoimmune, neurodegenerative, metabolic, and cardiovascular diseases." (PMID 32526825, 2020). "Sirtuin 1 (Sirt1) is a NAD+ dependent lysine deacetylase associated with the pathogenesis of various diseases including cancer." (PMID 32426286, 2020).
cancer (continued). "From The Cancer Genome Atlas (TCGA) tumor samples spanning 33 cancer types, we showed that the higher expression of SIRT1 was strongly associated with favorable OS." (PMID 32276460, 2020). "The overexpression of silent mating type information regulation 2 homolog 1 (SIRT1) in 5-FU resistant carcinoma cells has been implicated for the promotion of carcinogenesis and the development of drug resistance." (PMID 32503256, 2020). "SIRT1 is associated with an increase in lifespan and memory, and presents beneficial effects in metabolic syndrome, neurodegeneration and cancer." (PMID 30875794, 2019). "Decreased SIRT1 levels combined with elevated PIASy expression is implicated in more invasive types of cancers." (PMID 30761005, 2019). "Although SIRT1 participates in diverse cellular processes, the mechanisms underlying its precise role on DNA damage and repair and its contribution to cancer development remains underexplored." (PMID 31261609, 2019). "HuR leads to the promotion of cancer cell survival through stabilization of transcripts encoding anti-apoptotic factors like B-cell lymphoma 2 (Bcl-2), p21, and Sirtuin 1 (SIRT1)." (PMID 30850014, 2019). "Elevated expression of SIRT1 was observed in several cancer cell lines, and is generally associated with poor prognosis and overall survival." (PMID 30761005, 2019). "We previously reported that tNOX knockdown in T24 cells reversed cancer phenotypes in association with downregulation of SIRT1 and cyclin D1, even though the details of the underlying mechanism remained unclear." (PMID 31635402, 2019). "Sirtuins (SIRT1-7) play a significant role in cancer by regulating cancer-associated metabolism, modifying tumor microenvironment and affecting the response to genomic instability." (PMID 31757997, 2019). "Female cancer patients carrying the G minor allele of rs3740051 exhibited higher serum SIRT1 levels." (PMID 30714469, 2019). "Even though new functions of SIRT1 have been characterized, the underlying mechanisms that define its precise role on DNA damage and repair and their contribution to cancer development remains underexplored." (PMID 31261609, 2019). "Both height and SIRT1 have been associated with human longevity, possibly through influencing cancer risks." (PMID 30410074, 2018). "Previous studies on SIRT1 genetic variants in relation to cancer risk are scarce and were conducted in specific populations." (PMID 30410074, 2018). "New aspects of VD's mode of action affect SIRT1, a histone deacetylase implicated in cancer formation and autoimmune mechanisms." (PMID 30271381, 2018). "The expression of SIRT1 is up-regulated in multiple types of tumors and is associated with tumor resistance to cancer chemotherapy." (PMID 30451820, 2018). "As shown, cancer cells with SIRT1 depletion were positively associated with poor tumor differentiation (NES = −1.61, P<0.007)." (PMID 30038266, 2018). "Outside of cancer biology, SIRT1 de-regulation is associated with metabolic, neurodegenerative, and cardiovascular diseases." (PMID 29717261, 2018). "This study is one of few studies showing epidemiological data on associations between SIRT1 tagging SNPs and cancer risk." (PMID 30410074, 2018). "Cancer type had a significant influence on the overall association between SIRT1 expression and OS (P = 0.037), suggesting that cancer type mainly contributed to the heterogeneity in the overall analysis." (PMID 28977971, 2017).